ETV4 (ETS variant transcription factor 4)
Diseases named in the same sentence as ETV4 in open-access papers (continued):
Sharing a sentence is not in itself a finding about the gene and the disease.
gastric cancer (17 papers, 2008 to 2025). A primary or metastatic malignant neoplasm involving the stomach. "PEA3 sub-family member ETV4 mRNA expression was observed in 64% of a series of 100 gastric cancer patients and was associated with adverse pathologic features including lymphatic and vascular invasion and lymph node positivity." (PMID 41425714, 2025). "In liver and gastric cancer types, ETV4 positively modulates MMP1 by binding the MMP1 promoter regions." (PMID 32982961, 2020). "In gastric cancer, the level of ETV4 mRNA correlated significantly with tumor invasiveness and recurrence, while ETV1 and ETV5 expression were not related to survival." (PMID 29371979, 2017). "ETV4 is a TF of the E26 transformation‐specific (ETS) family and plays an important role in tissue development, promoting the growth and metastasis of gastric cancer." (PMID 39228892, 2024). "The regulatory function of TEAD4, ETV4, PRRX1, and FOXM1, over other key TFs and common DEGs, was highlighted in gastric cancer, establishing key co-regulatory complexes." (PMID 39228892, 2024). "ETS family members with the highest protein level of expression in many gastric cancer samples include ETV5, ETV4 and ETV3, while ELF2 and ELF3 had moderate to high levels of expression in all samples tested in the Human Protein Atlas but only in one of the two antibodies checked for each protein." (PMID 41425714, 2025). "Transcription factors MYB, MYBL2, ETV4, LEF1,TFAP2A were up-regulated in gastric cancer tissues." (PMID 25860484, 2015). "Specifically, five transcription factors MYB, MYBL2, ETV4, LEF1 and TFAP2A were up-regulated and they formed the TF-gene regulatory networks with 41 genes, 38 of which were up-regulated and 3 were down-regulated in gastric cancer tissues." (PMID 25860484, 2015). "In addition to tumor suppressors, we also observed several candidate oncogenes to be expressed at lower levels in EBVaGCs including 4 (CDH17, CDX1, ETV4, and PPP1R1B) known to be over expressed in gastric carcinoma and gastrointestinal cancers." (PMID 23671415, 2013).
ovarian carcinoma (17 papers, 2005 to 2025). A malignant neoplasm originating from the surface ovarian epithelium. "In ovarian cancer, the loss of repressors of the PEA3 subfamily was shown to cause overaccumulation of ETV4 and ETV5." (PMID 33671331, 2021). "However, in adults, ETV4 is rarely expressed in normal tissues, mainly appearing in tumor tissues such as those in breast, gastric, prostate, colon and ovarian cancers." (PMID 40777122, 2025). "In addition, the Fgf-responsive gene Etv4 and its close family member Etv5 are overexpressed in certain ovarian cancers." (PMID 28873404, 2017). "ETV4 expression was positively associated with majority of ICP genes in many cancers, such as ovarian cancer and PCPG, but negatively correlated in KIPAN and COAD.This finding implied that ETV4 might promote tumorigenesis and progression via breaking the balance of ICP." (PMID 37205199, 2023). "Similarly, ETV4 (PEA3) is overexpressed in cisplatin-resistant PEO1 ovarian cancer cells." (PMID 24624361, 2014). "We verified increased expression of Etv4 and Etv5 in MOSE-HRAS cells, suggesting that this model recapitulated the differences we observed in CCNE1 and RTK/RAS-driven ovarian cancers." (PMID 25557169, 2015). "Importantly, the expression of ETV4 was specific to the CIC-DUX4 CAM tumor, as ETV4 was not expressed in other types of CAM tumors derived by transplanting ovarian cancer cells or brain cancer cells." (PMID 34685592, 2021). "The coordinated expression of 3 sprouty family members, DUSP6, and ETV4 and 5 in a subset of ovarian cancers therefore raises the possibility that the activity of a specific, MAPK-related signaling pathway may have a role in ovarian cancer." (PMID 16042759, 2005).
Ewing sarcoma (16 papers, 2011 to 2025). A small round cell tumor that lacks morphologic, immunohistochemical, and electron microscopic evidence of neuroectodermal differentiation. "3,3′-Diindolylmethane was effective in reducing ETV1 and ETV4 transcripts, with both shown to promote Ewing’s sarcoma." (PMID 33918387, 2021). "Alternatively, EWSR1 can be fused with ERG, ETV1, E1A-F (alias ETV4) or FEV in Ewing sarcoma." (PMID 29416716, 2018). "It was later reported that Ewing sarcoma has more chromosomal translocations, including EWS/FLI fusion, EWS/ERG fusion, EWS/FEV fusion, EWS/ETV1 fusion, EWS/ETV4 fusion, FUS/ERG fusion, FUS/FEV fusion, and FUS/ETV4 fusion." (PMID 36964542, 2023). "For example, Ewing sarcoma translocations involve one of five closely homologous ETS family members (FLI, ERG, FEV, ETV1, and ETV4)." (PMID 34145397, 2021). "ETV4 is a well-established CIC-DUX4 target and cancer metastatic driver that has been used to distinguish CDS from the other Ewing sarcomas." (PMID 34642317, 2021). "The ERG related members include ETV1, ETV4, ETV5 and FLI1 which have been shown to overexpress in different diseases including CaP, Ewing sarcoma, and acute myeloid leukemia." (PMID 28191285, 2016). "Other fusion partners seen with Ewing sarcoma include FEV, ETV1, and ETV4." (PMID 40255709, 2025). "Most Ewing sarcomas harbor gene fusions involving the FLI1, ERG, ETV1, ETV4, or FEV gene." (PMID 21789226, 2011). "In the 15–20% of Ewing sarcomas that are negative for EWSR1–FLI1, variant fusions between EWSR1 (or rarely FUS gene) and other members of the ETS family occur, most commonly ERG (encoding transcriptional regulator ERG) followed by ETV1, ETV4, FEV and E1AF." (PMID 32295254, 2020). "Ewing Sarcoma (ES) is a primitive small round cell sarcoma defined by fusions involving members of the FET (predominantly EWSR1 or FUS) and ETS (most commonly including FLI1, ERG, ETV1, ETV4, or FEV) gene families." (PMID 35059992, 2022).
hepatocellular carcinoma (16 papers, 2021 to 2025). A malignant tumor that arises from hepatocytes. "PBK overexpression promotes the metastasis of hepatocellular carcinoma by activating the ETV4-uPAR signaling pathway." (PMID 33952716, 2021). "In hepatocellular carcinoma, ETV4 elevation facilitates tumor metastasis by upregulating PD-L1." (PMID 41318472, 2025). "To test this hypothesis, we first measured the expression of glucose transporters and key glycolytic enzymes after knockdown of ETV4 in two human hepatocellular carcinoma cell lines HepG2 and Huh7, which show high glycolytic activities." (PMID 34052833, 2021). "For instance, in hepatocellular carcinoma (HCC), HSPA8 functions as a co‐activator of the transcription factor ETV4, leading to the upregulation of PHLDA2, thereby facilitating the progression of liver cancer." (PMID 40099939, 2025). "ETV4 is a transcription activator of TNF‐α, promoting hepatic inflammation in hepatocellular carcinoma." (PMID 39228892, 2024). "Additionally, PBK promotes metastasis and resistance to oxaliplatin by regulating pathways such as ETV4-uPAR and PTEN in hepatocellular carcinoma." (PMID 37120564, 2023).
colon cancer (14 papers, 2004 to 2025). "Previous work shows that siRNA-mediated knockdown of ETV4 results in reduced colon cancer cell proliferation and invasion." (PMID 33407520, 2021). "ETV4 has an important role in cell motility and in the invasiveness of prostate, breast, and colon cancer cells through the regulation of matrix metalloproteinases (MMPs) that cause degradation of extracellular matrix." (PMID 32791988, 2020). "have determined that ETV4 can combine with the promoter of MMP1 to activate t its transcription, suggesting that the ETV4-related pathway may serve as a therapeutic target for colon cancer." (PMID 40469297, 2025). "The regulatory function of TEAD4, TCF3, ETV4, SOX4, and FOXM1, over other key TFs and common DEGs, was highlighted in colon cancer, establishing key co-regulatory complexes." (PMID 39228892, 2024). "Across the cohort, six fusion gene rearrangements were identified in cancers of the colon (TPM-NTRK1), bile duct (FGFR2), thyroid (BRAF) and prostate (ETV4-CLTC, and TMPRSS2-ERG)." (PMID 36213130, 2022). "PEA3 subfamily of ETS transcription factors (ETV1, ETV4, and ETV5) are upregulated in multiple cancers including colon cancers." (PMID 33658938, 2020). "After observing that ETV4 and ETV5 are overexpressed in colon cancerous tissue from TCGA cohort, we studied their role in predicting adjCTX response in colon cancer using three publicly available datasets." (PMID 33658938, 2020). "Our analysis revealed higher expression of ETV4 and ETV5 genes in colon cancer tissue compared to normal tissue in TCGA samples." (PMID 33658938, 2020). "In MSS tumours, ETV4, along with the β-catenin, induced MMP7 in intestinal and colon cancer cells." (PMID 34824625, 2021). "All of these results indicated that ETV4 could bind to the P4 fragment of the MMP1 promoter and transcriptionally activate MMP1 in colon cancer cells, which confirmed the MMP1/ETV4/MMP1 positive feedback." (PMID 34753916, 2021). "Combined with these findings, we speculated that MMP1 might accelerate the cell cycle transition of colon cancer cells by regulating cdc25a/CDK4-cyclin D1 and p21/cdc2-cyclin B1 complexes through alteration in the expression of c-Myc and ETV4." (PMID 34753916, 2021). "Additionally, we explored the role of ETV4 and ETV5 in 5-FU-based-adjCTX response prediction utilizing three publicly available colon cancer patient cohorts." (PMID 33658938, 2020).
sarcoma (12 papers, 2015 to 2025). A usually aggressive malignant neoplasm of the soft tissue or bone. "The expression of calretinin to varying degrees was observed in about 3/4 of CIC sarcomas, emphasizing that ETV4 has a positive expression rate of 70% in CIC-NUTM1 sarcomas, which is inconsistent with classical CIC sarcomas (positive rate of up to 100%)." (PMID 40255429, 2025). "Recent immunohistochemical analysis of the ETV4 gene shows the gene to be a useful marker for the detection of sarcomas with CIC rearrangement." (PMID 34685592, 2021). "These tumors displayed morphologic features similar to bona fide CIC-DUX4 sarcomas, namely lobulation, focal spindling, myxoid changes, distinct nucleoli, and positive ETV4 and WT1 immunohistochemical stains." (PMID 34898574, 2021). "It is believed that ETV4 positive is more likely to diagnose CIC-NUTM1 sarcoma than NUT carcinoma." (PMID 40255429, 2025). "The results suggest that WT1, calretinin and ETV4 may be useful markers for the differentiation of CIC rearrangement sarcoma and other small round cell tumors." (PMID 40255429, 2025). "In sarcomas, fusion proteins such as CIC-DUX4 promote malignant development by regulating pathways such as ETV4, and ETV4 is necessary for the invasion of cancer cells and metastasis." (PMID 40427614, 2025). "In sarcomas, fusion proteins such as CIC-DUX4 promote malignant development by regulating pathways such as ETV4, which is required for cancer cell invasion and metastasis." (PMID 40427614, 2025). "ETV4 expression, along with at least focal WT1 expression is helpful in distinguishing CIC-rearranged sarcoma from its differential diagnosis, although some challenges maybe encountered in optimizing the ETV4 antibody." (PMID 40722508, 2025). "On the contrary, ES, BCOR rearranged sarcoma, and poorly differentiated synovial sarcomas, are negative for both nuclear ETV4 and WT1 staining." (PMID 32155762, 2020). "Moreover, CIC-DUX4 sarcomas are characterised by consistent ETV1, ETV4, and ETV5 upregulation, and ETV4 immunohistochemistry has been identified as a highly sensitive marker for this tumour entity." (PMID 28680140, 2017). "All CIC-NUTM1 sarcomas except one expressed ETV4, while NUT cancer did not." (PMID 40255429, 2025). "External consultation indicated that the tumor cells were focally positive for WT1 and ETV4, consistent with CIC-rearranged sarcoma; however, CIC FISH did not identify the CIC gene rearrangement." (PMID 36033527, 2022). "These include sarcomas with BCOR alterations, CIC-rearranged sarcoma (see ‘WT1 and ETV4’), and round cell sarcoma with EWSR1-non-ETS fusions." (PMID 33921435, 2021). "The tumor had no expression of ETV4 and WT1, markers typically positive in CIC-rearranged sarcoma and which may be useful in this differential diagnosis." (PMID 34898574, 2021). "ETV-4 and WT-1 are positive in CIC-rearranged sarcomas, and they are negative for NKX2.2." (PMID 34722090, 2021).
glioma (9 papers, 2019 to 2025). A benign or malignant brain and spinal cord tumor that arises from glial cells (astrocytes, oligodendrocytes, ependymal cells). "Previous studies have found that mutations in CIC promote malignant progression of gliomas and that Etv4 is implicated in the transcriptional regulation of CIC." (PMID 34337051, 2021). "We analyzed the expression of the major ETS-factors ETS1, GABPA, and GABPB with its splice variants, ETV1, ETV4 and ETV5 all of which were widely expressed across our glioma cell panel." (PMID 31391125, 2019). "In addition, we performed CCK-8 assays, colony formation, Transwell invasion assays, apoptosis assays to determine the role of ETV4 in glioma." (PMID 40777122, 2025). "We found that inhibition of ETV4 attenuates cell proliferation and invasion in glioma cells." (PMID 40777122, 2025). "Moreover, we reported that inhibition of ETV4 attenuates cell proliferation and invasion in glioma cells." (PMID 40777122, 2025). "Notably, gliomas with Class I alterations were enriched for transcripts associated with MEK functional activation (e.g., ETV4, LZTS1), which can also be markers of MEK inhibitor sensitivity." (PMID 36854806, 2023). "Notably, one study showed that ETV4 expression increases with glioma grade progression." (PMID 40777122, 2025). "Hence, ETV4 downregulation inhibits cell viability, proliferation and invasion in glioma cells." (PMID 40777122, 2025). "However, the role of ETV4 in glioma development and progression remains largely uncharacterized." (PMID 40777122, 2025). "CIC protein levels inversely correlated with ETV4 in human neural progenitor cells (NPC) and glioma tumorspheres." (PMID 36647117, 2023). "Using microarray datasets from patients with different grades of glioma, we have analyzed the expression profiles of various ETS genes, and have identified ETV1, ELK3, ETV4, ELF4, and ETV6 as novel biomarkers for the identification of different glioma grades." (PMID 33671331, 2021). "The expression of ELK3, ETV4, and to some extent ELK4 was found to increase gradually with glioma grade, while ETV1 expression was highest in grade 2 glioma, and progressively decreased with glioma stage." (PMID 33671331, 2021). "We show that, while ETV1 is expressed at high levels in grade 2 glioma, its expression gradually decreases with glioma stage, and on the other hand, ELK3 and ETV4 expressions are increased with progression of the glioma stage." (PMID 33671331, 2021).
prostate tumors (8 papers, 2010 to 2023). "On the other hand, almost all the novel alternative ETV4 transcripts found in prostate cell lines and in human prostate tumors derive from exon skipping mechanism." (PMID 37002241, 2023). "Alternatively spliced genes are common in cancer cells: an analysis of the TCGA dataset confirms the abundance of these novel ETV4 transcripts in prostate tumors, in contrast to peritumoral tissues." (PMID 37002241, 2023). "This pattern of expression with such abundance of alternative ETV4 transcripts in prostate tumors is likely to be secondary to the deranged splicing machinery often present in tumors." (PMID 37002241, 2023). "For example, the Ddx5 gene is fused in frame to the ETV4 gene in prostate tumors." (PMID 24275493, 2014). "Thus, the abundance of alternative ETV4 transcripts seems specific of prostate tumors." (PMID 37002241, 2023). "Similar fusions that over-express the ETS genes ETV1, ETV4, and ETV5 occur in another 10% of prostate tumors." (PMID 24642271, 2014). "Most tumors, which would have been classified as ETS negative based on the exclusive assessment of the few ETS genes known to be translocated in prostate tumors (i.e., ERG, ETV1 and ETV4) had in fact significantly alterations of other ETS factors." (PMID 20479932, 2010). "This may reflect a unique role for ETV4, since a recent report indicates that expression of ETV4, but not other oncogenic ETS genes correlates with both PI3K and RAS signaling in prostate tumors." (PMID 24642271, 2014). "Despite the consistent reports on the involvement of either ETV1 or ETV4 in invasion and AIG in vitro, and comparing to what is accepted for other tumor types, validation of the contribution of these PEA3 members to an increased aggressiveness of prostate tumors is only emerging." (PMID 25595908, 2015).
liver cancer (7 papers, 2020 to 2025). An epithelial or non-epithelial malignant neoplasm that arises from the liver. "Lentiviral knockdown of CCL2 or the CCR2 inhibitor CCX872 significantly attenuated ETV4-induced invasion of TAMs and MDSCs and metastasis of liver cancer." (PMID 39816386, 2024).
non-small cell lung carcinoma (7 papers, 2013 to 2026). A group of at least three distinct histological types of lung cancer, including non-small cell squamous cell carcinoma, adenocarcinoma, and large cell carcinoma. "We previously found that oncogenic ETS variant transcription factor 4 (ETV4) overexpression is associated with DNA replication, glycolytic metabolism, tumor progression, and poor prognosis in non-small cell lung cancer (NSCLC)." (PMID 42100492, 2026). "ETV4 has also been previously implicated in regulating metastasis in non-small cell lung cancer through transcriptional control of extracellular matrix modifying enzymes." (PMID 36509998, 2023).
pancreatic cancer (7 papers, 2010 to 2025). "For example, overexpression of ETV4 has been shown to activate the CXCL13/CXCR5 axis, promoting pancreatic cancer metastasis, and ETV4 expression serves as an independent prognostic factor influencing patient survival." (PMID 40469297, 2025). "To further explore the in vivo effects of ETV4, we established a stable Panc02 sh-ETV4 pancreatic tumor cell line in mice." (PMID 40469297, 2025). "In pancreatic cancer and breast cancer, ETV4 directly upregulates the transcription of cyclin proteins, such as cyclin D1 and cyclin D3 to promote cell proliferation." (PMID 32018225, 2020). "ETV4 (ETS Variant 4) is a transcription factor belonging to the EST family and is specifically involved in the carcinogenesis of various tissues, including pancreatic cancer, breast cancer and intestinal cancer." (PMID 32018225, 2020). "Interestingly, our study found that knocking down ETV4 leads to an upregulation of FGL1 expression in RBE and SK-hep1 cells, while the opposite effect was observed in pancreatic cancer cells and tumors, where ETV4 knockdown resulted in the downregulation of FGL1 expression." (PMID 40469297, 2025). "In pancreatic cancer, the downregulation of FGL1 following ETV4 knockdown could potentially enhance the efficacy of immunotherapy by reducing immune suppression and improving T-cell activation." (PMID 40469297, 2025). "Indeed, a prior study suggested that overexpression of a single ETS TF confers resistance to MEKi trametinib in KRAS mutant pancreatic cancer, while suppression of ETV1, ETV4, or ETV5 alone strongly decreased the resistance." (PMID 32413516, 2020). "Moreover, we further validated the existence of a correlation between ETV4 and Fibrinogen-like protein 1 (FGL1), a major ligand for the inhibitory receptor LAG3, in pancreatic cancer, suggesting that the ETV4-FGL1 axis may be a key player in tumor immune evasion." (PMID 40469297, 2025). "Further RT-qPCR analysis of mouse tumor tissues demonstrated that knockdown of the ETV4 gene resulted in reduced FGL1 expression and no significant changes in HAVCR2, consistent with the results observed in BxPC3 pancreatic cancer cells." (PMID 40469297, 2025).